FGL2 (fibrinogen like 2)
Diseases named in the same sentence as FGL2 in open-access papers (continued):
Sharing a sentence is not in itself a finding about the gene and the disease.
glioblastoma (16 papers, 2015 to 2025). The most malignant astrocytic tumor (WHO grade IV). "Increased FGL2 expression is associated with tumour progression and poor survival in several different cancers, such as glioblastoma multiforme, lung, renal, liver, colorectal, and prostate cancer." (PMID 38191799, 2024). "FCGR3A and FGL2 are highly expressed in elderly individuals, glioblastoma patients (G4), those with tumor progression after initial treatment, and those with poor prognosis confirmed by OS, DSS and PDI." (PMID 39629005, 2024). "For example, FGL2 accelerated glioblastoma progression by promoting the proliferation of Treg cells and the polarization of macrophages in the tumor microenvironment, exerting an immunosuppressive effect." (PMID 38903931, 2024). "FGL2, a member of the thrombospondin family, is essential to regulate the activity of immune and tumour cells in glioblastoma (GBM)." (PMID 37990103, 2023). "Here, we show that T cells expressing fibrinogen-like 2 (FGL2)–specific single-chain variable fragments (T-αFGL2) can induce tumor-specific CD8+ TRM cells that prevent glioblastoma recurrence." (PMID 36759517, 2023). "FGL2 is already considered a potential molecular target for glioblastoma treatment." (PMID 33323552, 2020). "Some of the new cellular targeting approaches such as galectin-1 knock-down, IL-12 administration, anti-CCR2 or anti-FGL2 might be effective and beneficial for glioblastoma therapy because these can reduce numbers of both MDSCs and GAMs." (PMID 31225500, 2019). "Fibrinogen-like protein 2 (FGL2) is a secreted factor and is overexpressed in glioblastoma compared to LGGs." (PMID 33511267, 2020). "Moreover, FGL2 contributes to glioblastoma multiforme (GBM) progression by stimulating immunosuppression mechanisms." (PMID 32206449, 2020). "Fibrinogen-like protein 2 (FGL2) mediates immune suppression in glioblastoma (GBM)." (PMID 30683885, 2019). "Furthermore, tumor-derived Fibrinogen-like protein 2 (FGL2) suppresses the differentiation of CD103+ dendritic cells, thereby impairing CD8+ T cell-mediated immune responses against glioblastoma." (PMID 40076738, 2025). "A broad assessment of available human cancer cell lines by qPCR shows that FGL2 is not detected in epithelial cancer cell lines, but is detectable in glioblastoma cell lines, monocyte-derived THP-1 cells, and T cell-derived Jurkat cells." (PMID 38191799, 2024). "In vitro, downregulation of FGL2 in tumor cells did not affect tumor cell proliferation, but in an experimental glioblastoma mouse model with evidence of DCs with defective differentiation, downregulation of FGL2 impaired tumor progression." (PMID 38275375, 2023).
viral infection (16 papers, 2010 to 2025). "In summary, CD8+ T cell production of Fgl2 during viral infection underpinned an FcγRIIB-mediated loss of CD8+ T cell immunity in both mice and humans." (PMID 40197366, 2025). "In an experimental model of fulminant viral hepatitis, our laboratory showed that increased plasma levels of FGL2 pre- and post-viral infection were predictive of susceptibility and severity of disease." (PMID 23908776, 2010). "For FGL2 as the focus gene a similar pattern emerged, including an expanded cluster of signature enrichments related to interferon responses, including some derived from models of viral infection, and an additional association with monocyte/macrophage-derived signatures." (PMID 26362649, 2015). "Collectively, these findings indicate that during viral infection, Fgl2 produced by CD8+ T cells contributes to FcγRIIB‐mediated loss of immune function in CD8+ T cells in both murine models and humans." (PMID 41146434, 2025). "FGL2 is involved in modulating responses to tissue injury, malignancy, viral infection, acute allograft rejection, and autoimmune disease." (PMID 41146434, 2025). "In peritoneal cavities of women with endometriosis, concentrations of multiple cytokines increase, and specific factors (such as viral infections and cytokines) can induce high levels of FGL2." (PMID 33893391, 2021). "This indicates that CC10 treatment reduced liver injury after viral infection by inhibiting Fgl2 expression." (PMID 30619295, 2018). "Induction of FGL2 during viral infection has been established in animal models, showing that plasma FGL2 levels are considerably elevated 2 days after infection with lymphocytic choriomeningitis virus strain WE (LCMV-WE)." (PMID 30419833, 2018). "Fibrinogen-like protein 2 (Fgl2) is a pro-coagulant protein that is substantially induced in macrophages upon viral infection, and Fgl2 depletion represses murine hepatitis virus strain 3 (MHV-3) infection." (PMID 30619295, 2018). "As a result, the virus infection is unable to generate significant FGL2 accumulation in the liver and serum." (PMID 26367131, 2015). "Blocking the FGL2–FcγRIIB pathway with therapeutics may provide a novel treatment for chronic viral infections and cancer." (PMID 26241231, 2015). "Genes in this signature code for proteins that are viral infection restricting factors (e.g. Ifitm1, Ifitm3, Gbp7), that protect against cellular or environmental stress (e.g. Abcb1a, Car2, Ern1, Serpina3g) or that regulate immune activation processes (e.g. Fgl2, Anxa1, Havcr2)." (PMID 27883012, 2016). "RNA-Seq analysis demonstrated that Fgl2 was produced by murine virus-specific CD8+ T cells, with an increase in Fgl2 in CD8+ T cells elicited during chronic versus acute viral infection." (PMID 40197366, 2025). "In a mouse model of chronic viral infection, PD-1+ CD8+ T cell-derived Fgl2 also negatively regulates virus-specific T cell responses." (PMID 38902261, 2024). "As a member of the fibrinogen-like protein family, fibrinogen-like 2 (FGL2) possesses prothrombinase activity and immune regulatory functions in both viral infection and cancer development." (PMID 36759517, 2023). "Although Vsig4 deficiency did not seem to affect the basal expression level of these factors before viral infection, qRT-PCR data showed that MHV-3 infection super-induced Vsig4−/− PEMs to express Fgl2, Tnf, Il-1β, and Il-6." (PMID 29109438, 2017). "Blocking IL-1β activity reduces the virus-induced expression of fibrinogen-like protein-2 (FGL2) in macrophages, and limits the liver recruitment of CD45+Gr-1high neutrophils upon the virus infection." (PMID 26367131, 2015). "Furthermore, the studies show that inhibition of FGL2 improves outcomes to experimental hepatitis and thus provide impetus for generation of reagents to inhibit FGL2 in patients with acute and chronic hepatitis B and C virus infection either alone or in combination with present anti-viral agents." (PMID 23908776, 2010).
viral infection (continued). "Notably, only two genes correlated with the presence of viral RNA in iMOs: FGL2 and C15orf48, suggesting the absence of viral infection (abortive or productive) in these cells." (PMID 40920821, 2025).
hepatocellular carcinoma (12 papers, 2014 to 2025). A malignant tumor that arises from hepatocytes. "Given our results showing that sFGL2 blockage leads to DC activation in hepatoma, we then investigated the mechanism associated with sFGL2 abolition of DC activation by culturing immature BMDCs with 4 μg/mL recombinant murine FGL2 for 16 h, followed by stimulation with LPS for 12 h." (PMID 31409352, 2019). "Among them, Fgl2 was detected in activated HSC to regulate T-cell function in the patients with hepatic carcinoma, which also plays an important role in immune tolerance and immune response repression." (PMID 34440898, 2021). "The growth of both subcutaneously and orthotopically transplanted hepatomas was inhibited in Fgl2-knockout mice and those treated with the sFGL2 antibody, respectively, as compared with controls." (PMID 31409352, 2019). "T cells, dendritic cells (DCs), and related cytokines in the tumor microenvironment were comparatively analyzed in BALB/c and C57BL/6 mice bearing transplanted hepatomas harboring Fgl2-knockout or receiving sFGL2-antibody treatment." (PMID 31409352, 2019). "Interestingly, while FGL2 has been primarily studied in cancer and inflammatory diseases, its pro-apoptotic role in ENCCs contrasts with its tumor-promoting effects in cancers such as hepatomas and brain tumors." (PMID 40978140, 2025). "On the other hand, FGL2 is a multifunctional protein known for its role in modulating prothrombin activity and inducing immune tolerance, impacting viral hepatitis, liver fibrosis, hepatocellular carcinoma (HCC), and liver transplantation." (PMID 38816776, 2024). "Moreover, FGL2 promotes the growth and angiogenesis of human hepatocellular carcinoma (HCC) cells in mouse xenograft injected models." (PMID 28978925, 2017). "In one study using murine models of hepatocellular cancer, researchers investigated the role of FGL2 produced by stromal and immune cells rather than cancer cells in the TME." (PMID 38191799, 2024). "FGL2 can lead to phosphorylation of ERK and p38 through thrombin production and subsequent activation of PAR1 and PAR3, or JNK through activation of PAR2, and these late cellular activities promote survival and proliferation, tumor growth and angiogenesis in hepatocellular carcinoma." (PMID 36313679, 2022).
lung carcinoma (12 papers, 2017 to 2025). "have uncovered that FGL2 induces the activation of cancer‐associated fibroblasts (CAFs), contributing to lung cancer progression." (PMID 39400959, 2024). "In other cancers, FGL2 expression was associated with better prognostic outcomes and increased lung cancer infiltration of immune cells, such as CD8+ T cells, macrophages, B cells, and DCs." (PMID 37115694, 2023). "Depletion of FGL2 inhibited colorectal carcinoma progression and enhanced epithelial‐to‐mesenchymal transition in vitro and in vivo, and deficiency of host FGL2 was associated with reduced growth of lung cancer." (PMID 35029030, 2022). "Knockdown or silencing of FGL2 expression has also been shown to inhibit prostate and lung cancer growth in preclinical models." (PMID 37115694, 2023). "Stromal derived FGL2 facilitates the growth of lung cancer by imitating the tumor-promoting microenvironment instead of regulating tumor cells directly." (PMID 33867830, 2021). "FGL2 derived from the tumor matrix was reported to promote the occurrence and development of lung cancer." (PMID 33323552, 2020). "However, the diagnostic value of FGL2 in lung cancer is largely unknown." (PMID 32206449, 2020). "In clinical databases of lung cancer patients, FGL2 exhibited antitumor activities by activating CTLs in the tumor microenvironment of lung cancer." (PMID 32206449, 2020). "In the GEPIA database, high FGL2 expression was correlated with better overall survival (OS) in lung cancer (OS HR = 0.61, log-rank P = 0.0016, cutoff-high = 50%)." (PMID 32206449, 2020). "So, FGL2 affect KRAS by influencing immune status in tumor environment of lung cancer." (PMID 32206449, 2020). "So, FGL2 might affect EGFR by influencing immune status in tumor environment of lung cancer." (PMID 32206449, 2020). "FGL2 also increase cytotoxic CD8+ T cells and dendritic cells in the tumor environment of lung cancer." (PMID 32206449, 2020). "Fibrinogen-like protein 2 (Fgl2), a pleiotropic cytokine affecting multiple cellular functions, was found to be able to increase the aggregation of MDSCs through CXCL12 in lung cancer, and also induced the activation and pro-tumorigenic phenotype of CAFs, which are the main source of CXCL12 in TME." (PMID 40244052, 2025). "It was suggested that HCP5 may involve in the process of lung cancer by competing with PDL2 and FGL2." (PMID 29069717, 2017).
viral hepatitis (10 papers, 2010 to 2024). An acute or chronic inflammation of the liver parenchyma caused by viruses. "To examine the effects of FGL2 on development of adaptive immunity, we utilized a model of acute viral hepatitis caused by LCMV WE." (PMID 24146739, 2013). "Based on these studies we postulated that interference with the FGL2-FCγRIIB inhibitory pathway would enhance anti-viral immune innate and adaptive immune responses in the experimental model of acute viral hepatitis caused by LCMV-WE." (PMID 24146739, 2013). "In viral hepatitis, acute vascular xenograft rejection and cytokine-induced fetal loss syndrome, microthrombosis due to fgl2 is responsible for microvascular disturbance, resulting in ischemic injuries." (PMID 23554679, 2011). "FGL1 is primarily associated with liver regeneration, non-alcoholic fatty liver disease (NAFLD), and liver cancer, while FGL2 is known to be involved in viral hepatitis, liver fibrosis, HCC, and liver transplantation." (PMID 38816776, 2024). "The CD4+CD25+ regulatory T cells (Tregs) and their effector molecule FGL2 play a key role in susceptibility to HBV infection and in regulating the outcome of fulminant viral hepatitis in vivo." (PMID 30419833, 2018). "Our study found that Fgl2 was highly expressed in peripheral blood mononuclear cells (PBMCs) and in liver tissue of humans or mice with severe viral hepatitis, and was positively related to the severity of the disease." (PMID 30619295, 2018). "Fgl2 has been verified to play an essential role in the progression of fulminant viral hepatitis as we appreciate from previous reports." (PMID 30619295, 2018). "In view of the important role of Fgl2 in severe viral hepatitis, investigations concerning the regulation of Fgl2 will be beneficial in the search for new strategies for treatment of severe hepatitis." (PMID 30619295, 2018). "Other protein-encoding genes (FGL2, CTSB, TPP1, SLCO2B1, NARF and JTB) have disease related functions, such as viral hepatitis and ileum cancer." (PMID 28401895, 2017). "We provide evidence here for the first time that FGL2 plays a critical role in regulating both anti-viral T and B cells immune responses in acute viral hepatitis." (PMID 24146739, 2013). "In the current study, we utilized the well-established murine model of acute viral hepatitis caused by LCMV WE to examine the influence of FGL2 on adaptive T and B cell immunity." (PMID 24146739, 2013). "In experimental cytokine-induced fetal loss or viral hepatitis, TNF-α was demonstrated to promote fgl2 expression in endothelial cells of trophoblasts and decidua or in hepatic endothelial cells." (PMID 23554679, 2011). "Additionally, FGL1 has demonstrated potential as a disease biomarker in radiation and drug-induced liver injury as well as HCC, while FGL2 shows promise as a biomarker in viral hepatitis and liver transplantation." (PMID 38816776, 2024). "We and collaborators have a long standing interest in studying the role of fgl2 in viral hepatitis." (PMID 30619295, 2018). "FGL2 has been shown to be an important effector molecule of Treg cells and was demonstrated to play a key role in the pathogenesis of both experimental and human viral hepatitis." (PMID 23908776, 2010).
brain tumor (8 papers, 2019 to 2025). "A previous study demonstrated that FGL2 expression is associated with brain tumor progression through the immune system." (PMID 34154648, 2021). "Given the heterogeneous but typically high levels of FGL2 expression in GBM cells, we next wanted to analyze the specific role of FGL2 within tumor cells in brain tumor progression." (PMID 30683885, 2019). "As such, FGL2 is an attractive target for brain tumor immunotherapy." (PMID 36759517, 2023). "However, owing to their poor blood–brain barrier penetration, the potential of FGL2-blocking antibodies to suppress brain tumor progression is limited." (PMID 36759517, 2023). "These unexpected results suggest that FGL2 in tumor cells could serve as a potential therapeutic target for treating brain tumors and preventing tumor relapse." (PMID 30683885, 2019). "Here we show that knockout of FGL2 in tumor cells induces adaptive immune responses, resulting in 100% tumor suppression in GL261, DBT, and LLC brain tumor model systems." (PMID 30683885, 2019). "have demonstrated that FGL2 inhibits the differentiation of CD103+ dendritic cells (DCs) induced by granulocyte‐macrophage colony‐stimulating factor (GM‐CSF) by suppressing NF‐κB, STAT1/5 and p38 activation, consequently promoting the progression of brain tumours." (PMID 39400959, 2024). "In addition, whether it is the original brain tumor mouse model or the mouse brain infiltrating lymphocytes inoculated with GL261-FGL2, compared with the control model, the number of MDSC, M2 and CD39+Treg increased 72, indicating that FGL2 reinforces tumor immunosuppression." (PMID 33867830, 2021).
Fulminant hepatitis (8 papers, 2013 to 2022). Acute hepatitis complicated by acute liver failure with hepatic encephalopathy occurring less than 8 weeks after the onset of jaundice. "FGL2 has been shown to act as an immune responsive coagulant in settings such as foetal loss driven by Th1 polarized immune responses and fulminant hepatitis." (PMID 26362649, 2015). "(2015) demonstrated that TNF-α, C5aR and fibrinogen-like protein 2 (FGL2) contribute to coagulation in virus-induced fulminant hepatitis." (PMID 35573780, 2022). "From our previous study the gene of fgl2 contributed profoundly in MHV-3 induced fulminant hepatitis and is extensively expressed in macrophages and endothelium." (PMID 30619295, 2018). "Gene therapy targeting Fgl2 silencing showed that the survival rate of fulminant hepatitis mice increased from 0 to 33.3%." (PMID 30619295, 2018). "The increasing levels of sFGL2 in the acute phase of hepatitis in our study group supports the previous finding that FGL2 is involved in the pathogenesis and clinical outcome of fulminant hepatitis in animal models." (PMID 30419833, 2018). "Furthermore, the macrophage prothrombinase FGL2/fibroleukin is an important determinant of disease in MHV-3 induced fulminant hepatitis, and the coronavirus nucleocapsid gene mediates much of its effect by inducing FGL2/fibroleukin." (PMID 34578284, 2021). "Finally, p38 has been demonstrated to induce the expression of macrophage prothrombinase fibrinogen-like protein 2 (Fgl2), a protein crucial for the pathogenesis of fulminant hepatitis in MHV-3-infected mice." (PMID 27384577, 2016). "FGL2 together with C5aR and TNF-α contribute to coagulation and complement activation during MHV-3-induced fulminant hepatitis." (PMID 30419833, 2018).
Hepatitis (8 papers, 2010 to 2024). Inflammation of the liver. "Compared to wild mice, liver injury was significantly reduced in the hepatitis model of Fgl2-deficient mice." (PMID 39629005, 2024). "Research indicates that the expression level of FGL2 is closely linked to hepatitis severity, suggesting that FGL2 expression in PBMCs could serve as a potential marker for assessing hepatitis severity." (PMID 38816776, 2024). "FGL2 was reported to be not only significantly increased in hepatitis and nonalcoholic fatty liver but also highly expressed in liver cancer." (PMID 35136014, 2022). "The main mechanism of action by which IL-1β was triggered by ROS combined with TNF-α to activate NF-κB to induce FGL2 expression, which intensifies the progression of hepatitis." (PMID 35136014, 2022). "In addition, FGL2 overexpression has been linked with increased ERK1/2 phosphorylation, and the inhibition of ERK1/2 activity in a murine hepatitis model reduced the downstream functional activity of FGL2, with little effect on its production." (PMID 39062880, 2024). "The usefulness of injection of a neutralizing antibody or gene therapy against fgl2 has been demonstrated in diseases including MHV-3 hepatitis and graft rejection, which may attenuate fibrin deposition as well as the pathological injury and prevent mice from mortality." (PMID 24348769, 2014). "Additionally, FGL2 upregulates the expression of C-C motif chemokine ligand 2 (CCL2), IL-1β, IL-6, and TNF-α, promoting the differentiation of macrophages into M1-like pro-inflammatory macrophages and exacerbating liver inflammation and fibrosis." (PMID 38816776, 2024).